CPA6 (carboxypeptidase A6)
Description:
May be involved in the proteolytic inactivation of enkephalins and neurotensin in some brain areas. May convert inactive angiotensin I into the biologically active angiotensin II. Releases a C-terminal amino acid, with preference for large hydrophobic C-terminal amino acids and shows only very weak activity toward small amino acids and histidine.
Synonyms: CPAH; ETL5; FEB11
Tractability: Antibody: UniProt places it where antibodies can reach, with high confidence; UniProt predicts a signal peptide or a membrane-spanning region; its Gene Ontology location is reachable by antibodies, with medium confidence.
Gene: Protein-coding gene on chromosome 8 (67,422,038 to 67,746,378, reverse strand). Ensembl gene ENSG00000165078.
Subcellular location: Secreted, extracellular space, extracellular matrix
Gene Ontology:
Molecular function: metallocarboxypeptidase activity; carboxypeptidase activity; zinc ion binding
Biological process: proteolysis
Genetic constraint (gnomAD): Loss-of-function variants: 29 observed, 29.56 expected, observed/expected ratio (o/e) 0.98, 90% interval 0.73 to 1.34. The upper end of that interval is the gene's LOEUF score, 1.34, which puts it in group 5 of 6, group 1 being the genes least tolerant of losing a copy. Missense variants: 329 observed, 325.05 expected, observed/expected ratio (o/e) 1.01, 90% interval 0.92 to 1.11. Synonymous variants: 108 observed, 113.61 expected, observed/expected ratio (o/e) 0.95, 90% interval 0.81 to 1.12.
Gene-disease validity (ClinGen):
ClinGen rates the evidence that CPA6 causes each of these diseases.
epilepsy (autosomal recessive): Disputed. A brain disorder characterized by episodes of abnormally increased neuronal discharge resulting in transient episodes of sensory or motor neurological dysfunction, or psychic dysfunction.
epilepsy (autosomal dominant): Refuted.
Homologues: Orthologues: chimpanzee CPA6 (99% identical), macaque CPA6 (97% identical), dog CPA6 (91% identical), pig CPA6 (90% identical), guinea pig CPA6 (89% identical), rabbit CPA6 (87% identical), mouse Cpa6 (84% identical), rat Cpa6 (84% identical), tropical clawed frog cpa6 (68% identical), zebrafish cpa6 (65% identical), Caenorhabditis elegans T06A4.1 (35% identical), Drosophila melanogaster CG3108 (32% identical), and 19 more. Paralogues in human: CPA3 (39% identical), CPB1 (39% identical), CPA2 (38% identical), CPA4 (37% identical), CPB2 (37% identical), CPA1 (36% identical), CPA5 (35% identical), CPO (34% identical).
Diseases named in the same sentence as CPA6 in open-access papers:
CPA6 is named in the same sentence as 24 diseases in open-access papers, as found by Europe PMC text mining. Sharing a sentence is not in itself a finding about the gene and the disease. The quoted sentences say what the papers report.
epilepsy (6 papers, 2015 to 2025). "The CPA6 gene encodes the Carboxypeptidase A6 enzyme, and its mutations can predispose to various types of epilepsy." (PMID 36358356, 2022). "In total, 6 different rare mutations in CPA6 have been identified in patients with seizure disorders." (PMID 27050163, 2016). "Further, a mother with unexplained epilepsy and a child with epileptic encephelopathy have recently been identified with deleterious CPA6 mutations." (PMID 27050163, 2016). "Previously, epilepsy patients with mutations in CPA6 have been reported with brain malformations, intellectual disability and hippocampal sclerosis, suggesting that CPA6 is involved in brain development." (PMID 25875328, 2015). "Our experiments demonstrate that these mutations in CPA6 are deleterious and provide further evidence for the involvement of CPA6 mutations in the predisposition for several types of epilepsy." (PMID 25875328, 2015). "Following our initial discovery of CPA6 SNPs as risk alleles for familial FS and TLE, as well as for sporadic cases of TLE, we searched for CPA6 mutations in another form of epilepsy." (PMID 25875328, 2015). "Among the children without post-neonatal epilepsy, the one pathogenic variant identified was in CPA6, a candidate gene that may result in epilepsy with onset through 12–18 years of age, outside the window of follow-up in this cohort." (PMID 33846556, 2022). "Two mutations in the CPA6 gene were originally identified in patients with seizure disorders." (PMID 27050163, 2016). "Given the relationship between CPA6 mutations and epilepsy, studies to elucidate the substrates of CPA6 could shed new light on epileptogenesis." (PMID 27050163, 2016). "The exact substrates of CPA6 remain unknown, and further studies are needed to identify CPA6 substrates that explain how CPA6 mutations increase the likelihood of developing epilepsy." (PMID 25875328, 2015). "Based on the information from previous studies of CPA6 mutations in epilepsy patients, we hypothesized that loss of function mutations cause an increased susceptibility to epilepsy." (PMID 25875328, 2015). "While the mechanism by which CPA6 mutations predispose patients to epilepsy remain unclear, several studies have explored functions of other proteins mutated in TLE and JME patients." (PMID 25875328, 2015). "Interestingly, alterations in CPA6 have been identified in other human diseases unrelated to epilepsy, although it remains unclear if there is any causal relationship." (PMID 25875328, 2015). "Genes potentially associated with FS-related epilepsy include SCN1A, ADGRV1, SCN1B, SCN9A, GABRG2, GABRD, and CPA6." (PMID 35813073, 2022). "The CPA6 promoter is more extensively methylated in patients with focal epilepsy or FS, further supporting a relationship between this gene and seizure disorders." (PMID 25875328, 2015). "Therefore, we investigated the mRNA levels of potential substrates of CPA6 as well as several genes known to be regulated by neuronal activity or contribute to epilepsy in mammals." (PMID 27050163, 2016). "We hypothesize that CPA6 mutations are part of a complex pattern of inheritance that predisposes towards seizures and epilepsy in general, but not necessarily a specific subtype of epilepsy." (PMID 25875328, 2015). "The CPA6 gene is located on chromosome 8 and is not related to previously reported loci for JME or other types of epilepsy." (PMID 25875328, 2015).
temporal lobe epilepsy (4 papers, 2015 to 2025). A localization-related (focal) form of epilepsy characterized by recurrent seizures that arise from foci within the temporal lobe, most commonly from its mesial aspect. "SNP and missense mutations have been reported in the gene encoding carboxypeptidase A6 (CPA6) in patients with temporal lobe epilepsy, febrile seizures, and JME." (PMID 40564020, 2025). "Mutations in the human CPA6 gene that reduce enzymatic activity in the extracellular matrix are associated with febrile seizures, temporal lobe epilepsy, and juvenile myoclonic epilepsy." (PMID 27050163, 2016). "Subsequently, additional mutations in CPA6 have been reported in patients with temporal lobe epilepsy as well as juvenile myoclonic epilepsy." (PMID 27050163, 2016). "Mutations in the CPA6 gene have been identified in patients with temporal lobe epilepsy and febrile seizures." (PMID 25875328, 2015). "Recently, we reported SNP alleles and missense mutations in the gene encoding carboxypeptidase A6 (CPA6) in patients showing febrile seizures (FS) and temporal lobe epilepsy (TLE)." (PMID 25875328, 2015). "Another study investigated the carboxypeptidase A6 (CPA6) gene, associated with a recessive familial form of febrile seizures and temporal lobe epilepsy and in sporadic temporal lobe epilepsy." (PMID 37834053, 2023).
Duane syndrome (3 papers, 2010 to 2022). "Deletion of part of the CPA6 gene has been associated with the development of the Duane syndrome, which suggests that this enzyme plays a pivotal role in the migration and axonal guidance during embryonic development." (PMID 36297573, 2022). "It was reported that CPA6 mutations were closely related to the occurrence of Duane syndrome, a congenital eye movement disorder in which eye abduction is restricted or absent, and adduction is restricted." (PMID 32570281, 2020). "If mutations in CPA6 contribute to Duane syndrome, our results also suggest that Duane syndrome can be a chondrogenic rather than a myogenic or neurogenic developmental disorder." (PMID 20885977, 2010). "The presence of CPA6 in a condensation posterior to the eye, previously found in the mouse and suggested to be the lateral rectus muscle, was of particular interest as CPA6 had been implicated in Duane syndrome." (PMID 20885977, 2010). "Mutations in several genes, including CPA6, have been linked to Duane syndrome." (PMID 20885977, 2010). "The expression of CPA6 posterior to the eye, suggested to be the lateral rectus muscle, has been of particular interest since a disruption of the human CPA6 gene was implicated in Duane syndrome." (PMID 20885977, 2010). "In conclusion, a role for CPA6 in the etiology of Duane syndrome is here supported by its expression in a functionally unique and relevant chondrogenic precursor." (PMID 20885977, 2010). "The CPA6 gene is located within a genomic locus named DURS1, previously implicated in Duane syndrome." (PMID 20885977, 2010). "In order to study the role of CPA6 in zebrafish development, particularly the development of the VIth cranial nerve relevant to Duane syndrome, the zebrafish genome was screened for all A/B-type CPs using a bioinformatics approach." (PMID 20885977, 2010). "Of particular interest to this study was the conserved expression of CPA6 posterior to the eye, consistent with a role for CPA6 in the etiology of Duane syndrome." (PMID 20885977, 2010). "The reported chromosomal translocation disrupting the 5′ end of the CPA6 gene in a Duane syndrome patient might also affect promoter/enhancer elements of neighboring genes." (PMID 20885977, 2010). "Carboxypeptidase A6 (CPA6) is an extracellular protease that cleaves carboxy-terminal hydrophobic amino acids and has been implicated in the defective innervation of the lateral rectus muscle by the VIth cranial nerve in Duane syndrome." (PMID 20885977, 2010). "The possibility that a mutant CPA6 might be responsible for axon guidance defects leading to Duane syndrome prompted us to investigate the role of CPA6 in the zebrafish." (PMID 20885977, 2010). "The conserved expression of CPA6 in cartilaginous precursors posterior to the eye, however, strongly suggests a role in the development and innervation of the lateral rectus and in the etiology of Duane syndrome." (PMID 20885977, 2010). "Recent reports have suggested that CPA6 may not be the sole causative Duane syndrome gene on chromosome 8, but the duplication of another more centromeric gene, CHD7, may be involved." (PMID 20885977, 2010). "We propose that CPA6 may be involved in the etiology of Duane syndrome through expression in a relevant chondrogenic condensation, but dysfunction of additional genes and/or evolutionary modification of axon guidance is required for the manifestation of a phenotype." (PMID 20885977, 2010). "Decreased expression of both CPA6 and DEPDC2 might produce a cumulative effect resulting in a Duane syndrome-like phenotype." (PMID 20885977, 2010). "Indeed, if CPA6 is found to be involved in the etiology of Duane syndrome, our data suggest that this syndrome is not always myogenic or neurogenic, but can also be a chondrogenic disorder." (PMID 20885977, 2010).
Duane syndrome (continued). "Another possibility for the lack of a CPA6 knockdown phenotype may be the involvement of other genes, acting in a compensatory manner in the zebrafish, or defective in reported cases of Duane syndrome but yet undetected." (PMID 20885977, 2010).
juvenile myoclonic epilepsy (3 papers, 2015 to 2020). "In the present study, we screened for CPA6 mutations in patients with juvenile myoclonic epilepsy and identified two novel missense mutations: Arg36His and Asn271Ser." (PMID 25875328, 2015). "In addition, CPA6 mutations were also identified in patients with juvenile myoclonic and epilepsy." (PMID 32570281, 2020).
diabetes mellitus type 2 (2 papers, 2020 to 2021). "It was also reported that CPA6 gene mutations were also related to the response to metformin in patients with type 2 diabetes." (PMID 32570281, 2020).
hepatocellular carcinoma (2 papers, 2020 to 2022). A malignant tumor that arises from hepatocytes. "In addition to being associated with to non‐tumour disorders, CPA6 expression had also been found to be dysregulated in several types of cancer, such as hepatocellular carcinoma and oral squamous cell carcinoma." (PMID 32570281, 2020). "CPA6 could promote cell proliferation and migration through regulating the AKT signaling pathway in hepatocellular carcinoma." (PMID 35686102, 2022).
oral squamous cell carcinoma (2 papers, 2020). "An early research reported that CPA6 was remarkably up-regulated in early stage samples with oral squamous cell carcinoma (OSCC) compared with those in late stage, suggesting that this gene might have crucial diagnostic values for OSCC." (PMID 32448271, 2020).
colitis (1 paper, 2022). Inflammation of the colon. "Although CPA6 is closely associated with the extracellular matrix or immune response, its expression was decreased in colitis." (PMID 35893911, 2022).
colorectal cancer (1 paper, 2025). A primary or metastatic malignant neoplasm that affects the colon or rectum. "Inhibiting Carboxypeptidase A6 (CPA6) expression in colorectal cancer can suppress Akt/mTOR signaling activation and inhibit tumor growth." (PMID 41001032, 2025).
epileptic syndromes (1 paper, 2015). "It is plausible to hypothesize that CPA6 defects are more involved in the onset of epileptic syndromes than in disease severity." (PMID 25875328, 2015).
focal epilepsy (1 paper, 2015). A seizure caused by a localized disorder. "A missense mutation (Ala270Val) in CPA6 has also been identified in a family with FS and focal epilepsy." (PMID 25875328, 2015). "Mutations in both the EFHC1 and CPA6 genes have been found in patients with generalized and partial epilepsies." (PMID 25875328, 2015).
generalized epilepsy (1 paper, 2015). Epilepsy that is characterized by generalized seizure types and may have typical interictal and/or ictal EEG findings that accompany generalized seizure types (for example generalized spike-wave). "In the present study we report two additional CPA6 mutations in JME patients who also presented with generalized epilepsy." (PMID 25875328, 2015).
prostate carcinoma (1 paper, 2025). A carcinoma that arises from epithelial cells of the prostate gland. "Finally, 21 biomarkers derived from web-based algorithm were screened, in which 5 genes have never been studied in prostate cancer research, including CPA6, KRT15, SMIM10, SPON1, and ST6GALNAC4." (PMID 41081583, 2025).
cancer (4 papers, 2018 to 2025). A tumor composed of atypical neoplastic, often pleomorphic cells that invade other tissues. "The probability of these six genes to be mutated in normal tissue adjacent to cancer is CPA6 (3.85%), ZNF888 (46.15%), SH3BP1 (76.92%), ANKRD16 (30.77%), ATN1 (11.54%), and C4orf54 (80.77%)." (PMID 40688112, 2025).
tumor (4 papers, 2020 to 2025). "Based on the TCGA database, we found that CPA6 acted as a tumour suppressive role and improved the OS of CRC patients." (PMID 32570281, 2020). "Comparing the expression of SH3BP1, CPA6, ZNF888, and NKRD16 in COAD and READ tumor and normal tissues revealed that SH3BP1 expression increased in COAD and READ and was more prevalent in tumor tissues than in the other susceptibility genes obtained by whole-genome sequencing." (PMID 40688112, 2025). "However, the role of CPA6 in CRC and even UC‐related tumours is unknown." (PMID 32570281, 2020). "For example, ALDH1A2 was positively correlated with CPA6 (r = 0.5, p < 0.0001) in tumor tissues, while in normal tissues, ALDH1A2 expression was negative (r = −0.63, p < 0.0001) correlated with CPA6." (PMID 41081583, 2025).
CPA6 also shares sentences with these, for which no sentence is quoted: brain malformations (1 paper); colon cancer (1); eye movement disorder (1); Intellectual disability (1); migraine (1); osteosarcoma (1); Primary hemophagocytic lymphohistiocytosis (1); Seizure (1); ulcerative colitis (1).